PCDHB12 (protocadherin beta 12)
Description:
Potential calcium-dependent cell-adhesion protein. May be involved in the establishment and maintenance of specific neuronal connections in the brain.
Synonyms: PCDH-BETA12
Tractability: Antibody: its Gene Ontology location is reachable by antibodies, with high confidence; UniProt places it where antibodies can reach, with medium confidence; UniProt predicts a signal peptide or a membrane-spanning region; the Human Protein Atlas places it where antibodies can reach.
Gene: Protein-coding gene on chromosome 5 (141,208,697 to 141,212,571, forward strand). Ensembl gene ENSG00000120328.
Subcellular location: Cell membrane
Subcellular location (Human Protein Atlas): Plasma membrane
Gene Ontology:
Molecular function: protein binding; cell adhesion molecule binding; calcium ion binding
Biological process: cell adhesion; nervous system development; homophilic cell-cell adhesion
Cellular component: plasma membrane; membrane
Genetic constraint (gnomAD): Loss-of-function variants: 0 observed, 0.0749 expected, observed/expected ratio (o/e) 0, 90% interval 0 to 1.89. That is too few expected variants to judge how well the gene tolerates losing a copy. Missense variants: 1,192 observed, 1,019.5 expected, observed/expected ratio (o/e) 1.17, 90% interval 1.11 to 1.23. Synonymous variants: 560 observed, 451.37 expected, observed/expected ratio (o/e) 1.24, 90% interval 1.16 to 1.33.
Homologues: Orthologues: mouse Pcdhb19 (74% identical). Paralogues in human: PCDHB11 (89% identical), PCDHB14 (76% identical), PCDHB7 (75% identical), PCDHB3 (75% identical), PCDHB13 (74% identical), PCDHB2 (74% identical), PCDHB4 (74% identical), PCDHB5 (74% identical), PCDHB16 (74% identical), PCDHB8 (73% identical), PCDHB15 (73% identical), PCDHB9 (73% identical), and 49 more.
Diseases named in the same sentence as PCDHB12 in open-access papers:
PCDHB12 is named in the same sentence as 3 diseases in open-access papers, as found by Europe PMC text mining. Sharing a sentence is not in itself a finding about the gene and the disease. The quoted sentences say what the papers report.
tumours (1 paper, 2009). "PCDHB8 and PCDHB15 exhibited strong methylation associated silencing but PCDHB12 was not consistently down-regulated in tumours, despite hypermethylation." (PMID 19956686, 2009).
PCDHB12 also shares sentences with these, for which no sentence is quoted: breast carcinoma (1 paper); cancer (1).